HMGB1 (high mobility group box 1)
Diseases named in the same sentence as HMGB1 in open-access papers (continued):
Sharing a sentence is not in itself a finding about the gene and the disease.
tumor (continued). "For example, as to the pro-tumor roles, HMGB1 induced the tumorigenesis such as sustenance of cell proliferation, differentiation, angiogenesis, metastasis, inflammation, and enhanced immunofunction in in vitro and in vivo HCC models." (PMID 26393575, 2015). "This was in part dependent on HMGB1, because no upregulation of the activation markers was observed when using DCs of MyD88 KO mice (Figures 4a1 and b1) or when incubating the tumor cell SNs with anti-HMGB1 antibody, respectively." (PMID 25973681, 2015). "This action was due to HMGB1 binding to TLR4 or RAGE, as pretreatment of the supernatant with anti-HMGB1 or pretreatment of the live tumor cells with anti-TLR4/RAGE markedly inhibited sCLU induction." (PMID 26469759, 2015). "Endogenous knockdown of HMGB1 with siRNA or inhibition of its release with small-molecule inhibitors, abolished the protective effect of autophagy and increased tumor cell sensitivity to several clinically useful agents." (PMID 25652880, 2015). "Available information indicates that the HMGB1 protein has diverse biological functions ranging from inflammation, genome stability, proliferation, cell death, autophagy, to tumor metastasis." (PMID 25051367, 2014). "HMGB1 can be produced by both tumor cells and stromal cells and is released into the extracellular environment from stressed and dying cells." (PMID 25512109, 2014). "Tumor angiogenesis is enforced by autocrine regulation of HMGB-1 in EC through increased expression of key pro-angiogenic genes as PDGF-A, FGF and MMP-2, that we found to be strongly up-regulated in tumors from hCD31 mAb treated mice." (PMID 25362644, 2014). "High-mobility group box 1 (HMGB1) activates the FAK/PI3K/mTOR signaling cascade and regulates tumor-associated cell migration through the interaction with BTB domain." (PMID 24524196, 2014). "The released HMGB1 activates division of surviving cancer cells, maintains inflammatory condition, stimulates the formation of tumor microenvironment towards angiogenesis." (PMID 24487722, 2014). "Radiation induces the translocation of CRT on the tumor cell surface along with the release of the DAMPs HMGB1 and ATP." (PMID 25506582, 2014). "Released HMGB1 that acts as a proinflammatory cytokine from necrotic tumor cells creates a microenvironment and triggers signaling pathway, such as the NF-κB and inflammasome, to induce proinflammatory cytokine release." (PMID 25356587, 2014). "Research has shown that depletion of HMGB1 in mouse xenograft tumors prevents anthracycline-induced anti-tumor activity, which is restored by exogenous recombinant HMGB1 protein." (PMID 24432020, 2014). "The protein levels of HMGB1 in HCC were significantly higher than those in para-tumor tissues (p = 0.005)." (PMID 25356587, 2014). "Both endogenous and exogenous HMGB1 have been considered as vital regulators of autophagy in tumor cells." (PMID 24996221, 2014). "HMGB1 can be released passively from dying tumor cells after chemotherapeutic treatment or following tumor cell lysis by the action of lymphokine-activated killer cells." (PMID 25512109, 2014). "The protein level of HMGB1 in HCC was significantly higher than those in para-tumor tissues, the pooled mean difference was 0.51 with 95% CI 0.16–0.86, (Z = 2.83, p = 0.005, heterogeneity I2 = 98%)." (PMID 25356587, 2014). "In contrast, there is the evidence that chemotherapeutic drug-induced HMGB1 can mediate the activation of innate immunity and tumor clearance." (PMID 25512109, 2014). "By synergizing with HMGB1, released from dying tumor cells and signaling through toll-like receptor (TLR) 4, activated DC are licensed to prime an anti-tumor immune response in a caspase-1- and IL-1β-dependent manner." (PMID 24795727, 2014). "Cytosolic translocation and HMGB1 release from tumor cells in response to chemotherapy and radiotherapy is a vital characteristic of the disordered tumor microenvironment." (PMID 24996221, 2014).
tumor (continued). "Following D-K6L9 peptide administration, we observed necrosis in tumor tissue as well as release of HMGB1 protein into extracellular space." (PMID 24487722, 2014). "In one study of a tumor-burdened rat model after thermal injury, excessive release of HMGB1 was found to stimulate splenic Tregs." (PMID 24837834, 2014). "In one study of a tumor-burdened rat model after thermal injury, the release of excessive HMGB1 after burn injury was found to activate splenic Treg cells." (PMID 24837834, 2014). "HMGB1 is not only constitutively expressed in the nucleus of cancer cells, but also is released by the tumor cells, macrophages, monocytes, dendritic cells (DCs), and T cells." (PMID 25356587, 2014). "Data collected here demonstrated that the expression of HMGB1 in cervical lesions increased with tumor progression." (PMID 24837834, 2014). "HMGB1 is constitutively expressed in the nucleus of cells, and also can be released outside by tumor cells and by inflammatory cells." (PMID 24510323, 2014). "tumor cells and tumor-infiltrating leukocytes secret HMGB1 in tumor microenvironment which activates NK-κB and inflammatory pathways, promoting tumor growth, invasion and metastasis; 2)." (PMID 25356587, 2014). "Since surviving cancer cells and released HMGB1 protein can be responsible for tumor relapse, the proposed therapy involved factors that destroy the remnant cancer cells and that inhibit HMGB1." (PMID 24487722, 2014). "Secreted HMGB1 functions in the repair of tissue damage and chronic inflammation and leads to increased tumor growth and metastasis, promotes angiogenesis, regulates vascular remodeling, and enhances stem cell renewal." (PMID 24723911, 2014). "In our study, reduced HMGB1 significantly inhibited tumor growth following docetaxel treatment in vivo." (PMID 24996221, 2014). "HMGB1 released from cancer cells induces autophagy in the muscle, which sustains anaerobic energy production (namely the Warburg effect) during tumor growth in vitro and in vivo." (PMID 25126737, 2014). "Experimental data have shown that through the activation of various signaling pathways such as NF-кB, Racl/Cdc42, MAPKs, PI3K/Akt, ERK1/2, SrcK, and HMGB1-RAGE interaction is deeply involved in tumor growth, migration, and metastases." (PMID 24510323, 2014). "It is likely that HMGB1 released into the microenvironment as a result of tumour cells induced by radiation facilitates the activation of dendritic cells within the tumour." (PMID 25097859, 2014). "Constant release of HMGB1 outside the cells, as a damage-associated molecular pattern (DAMP), creates a tumor microenvironment, which contributes to the development of epithelial malignancies." (PMID 24510323, 2014). "Extracellular HMGB1 mediates chronic inflammatory condition, formation of new tumor microenvironment and angiogenesis." (PMID 24487722, 2014). "TUNEL staining of resected tumor tissues also revealed even lower apoptosis in the HMGB1 shRNA group than the control group." (PMID 24996221, 2014). "HMGB1 also has the ability to increase the production of ATP and provide more energy for tumor growth; 3)." (PMID 25356587, 2014). "And the expression of Hmgb1 mRNA was significantly decreased in anti-γδ TCR treated wild-type mice or IL-17−/− mice bearing B16 tumor compared with control group." (PMID 24453427, 2013). "Hmgb1, a damage-associated molecule, and its receptor RAGE increased in tumor tissues 2 weeks after B16-F10 inoculation." (PMID 24453427, 2013). "HMGB1 is actively produced by macrophages and monocytes; it is passively released by damaged or necrotic cells and is thought to be involved in tumor cell invasion and metastasis." (PMID 23803172, 2013). "This type of cell death is characterized by the extracellular release of ATP and HMGB1, by the surface translocation of calreticulin, and by the subsequent phagocytosis of tumor cells by dendritic cells (DCs)." (PMID 24225025, 2013).
tumor (continued). "In this study, they showed that targeting HMGB1 disrupts tumor progression by inhibiting activation of T-cells and reducing infiltration of macrophages, which are considered to be key inflammatory cells in promoting variety of cancers including PCa." (PMID 23766911, 2013). "It is interesting to note that the radiation-induced release of HMGB1 by dying tumor cells enables the manifestation of tumor antigen-specific T cell immunity." (PMID 23378947, 2013). "HMGB1 has also been demonstrated to be released into the extra cellular medium and to exhibit important effects in the mediation of tumor growth, angiogenesis and metastasis." (PMID 23426143, 2013). "HMGB1 was previously reported to enhance the invasion ability of tumor cells through a VEGF-C-related pathway, and HMGB1 promotes lymphangiogenesis in human lymphatic endothelial cells." (PMID 23866030, 2013). "HSPs exposed by tumor cells can be recognized by TLR4 expressed on DCs, which facilitates activation, intracellular antigen-processing and -presentation in DCs; and CRT and HMGB1 exposed on ethanol-treated tumor cells serve “eat-me” signals." (PMID 23717436, 2013). "The constant release of the pro-inflammatory cytokine HMGB1 from necrotic tumor cells creates a microenvironment similar to chronic inflammation and contributes to the development of epithelial malignancies." (PMID 23866030, 2013). "Hmgb1 can induce chronic inflammatory-reparative responses and lead to tumor cell expansion and metastases." (PMID 24453427, 2013). "In a completely different mechanism, TIM3 expressed by tumor-infiltrating DCs was shown to interact with the alarmin HMGB1, disturbing the recruitment of tumor cell-derived nucleic acids into DC endosomes, attenuating immune responses to these tumors." (PMID 23450201, 2013). "Apoptosis of cancer cells has been reported to induce adaptive anti-tumor immune response through expression of some molecules, such as surface calreticulin, Hsp70, Hsp90 and soluble HMGB1 (high-mobility group box 1 protein)." (PMID 23935988, 2013). "When HMGB1 binds to its’ receptor RAGE (receptor for advanced glycation end-products) it promotes tumor growth and metastasis." (PMID 24098490, 2013). "The release of HMGB1 by MV-infected tumor cells is of particular interest as it has been shown to be a potent DAMP important for immunogenic cell death of cancer cells, acting as an adjuvant to DC maturation through the TLR4 pathway." (PMID 24832799, 2013). "One mechanism of achieving this enhanced T-cell activation following tumor irradiation is via the secretion of the HMGB1 protein by dying irradiated tumor cells and binding of HMGB1 on TLR4 expressed by dendritic cells." (PMID 24324970, 2013). "The second is the secretion of an endogenous Toll-like receptor 4 (TLR4) ligand High-mobility group box 1 (HMGB1), which is required for efficient processing of tumor antigen by dendritic cells." (PMID 23762310, 2013). "The significance of this pathway in vivo was indicated by the observation that blockade of the Hmgb1/RAGE interaction suppressed tumor growth." (PMID 24453427, 2013). "Tumour cells undergoing immunogenic cell death are characterized by the early surface exposure of calreticulin 33 and HSPs and by the late release of HMGB1." (PMID 23551576, 2013). "HMGB1 can function during inflammation, tumor invasion and metastasis through its receptors: RAGE and TLRs." (PMID 22747650, 2012). "In conclusion, the activation of PI3K pathway elicited by ER stress induced CRT/Annexin A1 translocation (“eat me” signal) and HMGB1 release, mediating wogonin-induced immunity of tumor cell vaccine." (PMID 23251389, 2012). "Conceptually, apoptotic death of tumor cells is predicted to conceal HMGB1 from TLR4-mediated recognition." (PMID 23087904, 2012). "The levels of HMGB1 mRNA and protein in tumor, para-tumor and normal tissue were evaluated in 11 HCC cases by Reverse Transcription-polymerase chain reaction (RT-PCR) and Western blot." (PMID 22747650, 2012).
tumor (continued). "HMGB1 protein was constitutively expressed in the nucleus of tumor cells, and also can be released by inflammatory cells and by tumor cells." (PMID 22747650, 2012). "An increasing body of evidence suggests that HMGB1 is associated with tumor metastasis and poor prognosis, making HMGB1 an attractive target as a tumor biomarker." (PMID 22496788, 2012). "Constant release of HMGB1 as a proinflammatory cytokine from necrotic tumor cells would create a microenvironment similar to chronic inflammations, and this condition was known to contribute to the development of epithelial malignancies." (PMID 22747650, 2012). "Although high and widespread overexpression of HMGB1 is found in tumor cells, only 20% of all patients had serum HMGB1 levels higher than the cutoff value of ROC curve (58.2 ng/mL)." (PMID 22496788, 2012). "In contrast, tumor cells passively release HMGB1 when they undergo either sustained autophagy, late apoptosis, or necrosis." (PMID 22891162, 2012). "HMGB1 was also identified as a specific marker of tumor endothelium and as a tumor angiogenesis marker." (PMID 23118492, 2012). "High mobility group box 1 (HMGB1) is a prototypical “alarmin” that was shown to be a central mediator in the immunogenicity of dying tumor cells following irradiation." (PMID 23087904, 2012). "Multivariate analysis indicated that expression of HMGB1 (p = 0.018, HR = 1.622; 95%CI: 1.088-2.419) and tumor size (p = 0.012, HR = 1.661; 95%CI: 1.119-2.465) were independent prognostic factors for disease-free survival." (PMID 22747650, 2012). "Previous results suggested that HMGB1 is an important mediator for precancerous disease, and therefore, HMGB1 can contribute to the early development of cancer, tumor growth, and invasion of cancer cells." (PMID 22496788, 2012). "HMGB1 released by dying tumor cells after doxorubicin or oxaliplatin treatment acts upon toll-like receptor 4 (TLR4) on dendritic cells to initiate efficient antigen processing and presentation that involves the Myd88-signaling pathway." (PMID 22400040, 2012). "The aim of present study was to analyze HMGB1 protein expression in tumor, para-tumor and normal tissue and to assess its prognostic significance for HCC after curative hepatectomy." (PMID 22747650, 2012). "In present study, we evaluated the expression of HMGB1 in tumor, para-tumor and normal tissue, to assess its prognostic significance in HCC patients after curative hepatectomy." (PMID 22747650, 2012). "The connection that widely exists between HMGB1 and intracellular signal pathways makes HMGB1 can function during inflammation, cell differentiation and migration, tumor invasion and metastasis." (PMID 22747650, 2012). "Among tumor samples, HMGB1 expression was scored 1–2 in 13 (8.1%), 3–4 in 21 (13.0%), 6–8 in 58 (36.0%), 9–12 in 50 (31.1%) and 16 in 19 (11.8%) specimens." (PMID 22747650, 2012). "Multivariate analysis showed that expression of HMGB1 (p = 0.009, HR = 1.834; 95%CI: 1.167-2.881) and tumor size (p = 0.005, HR = 1.902; 95%CI: 1.209-2.992) were independent prognostic factors for overall survival." (PMID 22747650, 2012). "High expression of HMGB1 in tumor is strongly correlated with incomplete tumor encapsulation and advanced TNM stage." (PMID 22747650, 2012). "High expression of HMGB1 was detected in 69/161(42.9%) of tumor tissues, and only 5/60(8.3%) in para-tumor tissues." (PMID 22747650, 2012). "In present study, we conducted the RT-PCR, Western blot and immunohistochemical methods to detect the expression of HMGB1 in tumor, para-tumor and normal tissues." (PMID 22747650, 2012). "Considering the known role of HMGB1, secreted HMGB1 can be involved in tumor metastasis through binding cell surface receptors including RAGE." (PMID 22496788, 2012). "It is also believed that optimal therapeutic effects require the immunoadjuvant effect of DAMPs like HMGB1 released from tumor cells damaged by cytotoxic anticancer agents." (PMID 21854645, 2011).
tumor (continued). "The group of Zitvogel extensively studied the effects of chemotherapy and showed that HMGB-1 released from dying tumor cells acted as a TLR4 agonist to activate APC." (PMID 22176642, 2011). "The specific immune modulating properties of proteins released from dying tumor cells (e.g. HMGB-1) on the activation of M2 macrophages via PAMP-receptors is not yet studied." (PMID 22176642, 2011). "CRT, HSPs and HMGB1 can function as immunological adjuvants for phagocytosis, cross presentation of tumor-derived antigens and antigen processing and presentation by DCs." (PMID 21689407, 2011). "HMGB1 stimulation of dendritic cells was necessary for processing and cross-presentation of antigens from dying tumor cells." (PMID 22151962, 2011). "Reduced HMGB1 induces Beclin1-dependent autophagy and promotes tumor resistance to several chemotherapeutic agents, whereas oxidized HMGB1 induces apoptosis via the mitochondrial caspase-9/-3 pathway." (PMID 21917150, 2011). "They demonstrated that TLR4 is essential for efficient tumor antigen cross-presentation following radio- or chemotherapy and proposed that HMGB1 binds and activates TLR4 on DCs." (PMID 22110526, 2011). "Interaction of TLR4 binding partners, which have been secreted by tumor cells (so-called danger signals, e.g. HMGB1) activate leukocytes through the differential engagement of multiple surface receptors like TLR4 and RAGE." (PMID 21854645, 2011). "The MDAs colchicine, CMQ and FMQ induced the expression of HSP70, HSP90 and HMGB1 in tumor cells as compared with cells treated with vehicle control, but did not affect the expression of CRT." (PMID 21689407, 2011). "On the other hand, HMGB1 released from irradiated or doxorubicin-/oxaliplatin- treated cells can improve immunogenicity of dying tumor cells and therefore help improve tumor antigen presentation." (PMID 22110526, 2011). "In the case of tumors, HMGB1 recognition has a paradoxical dual effect: the reparative inflammatory response promotes tumor neoangiogenesis, cell survival, expansion, and metastases; on the other hand, it triggers protective anti-neoplastic T-cell responses." (PMID 20579387, 2010). "In the study, the rate of HMGB1 overexpression tended to increase correlated with invasion depth, tumor stage, and lymph node." (PMID 20579387, 2010). "The HMGB1 pathway is not well understood at the mechanistic level, so our model can provide some insights into the study of HMGB1's roles in tumor proliferation." (PMID 21106117, 2010). "HMGB1 can also influence a variety of important cell types within the tumor microenvironment, including fibroblasts, leukocytes, and vascular cells." (PMID 20579387, 2010). "The interaction of HMGB1 released from dying tumor cells with Toll-like receptor 4 (TLR4) on dendritic cells (DCs) was required for the cross-presentation of tumor antigens and the promotion of tumor specific cytotoxic T-cell responses." (PMID 20579387, 2010). "Because HMGB1 has a dual effect on tumor progression, the feasibility of targeting the release of HMGB1 remains elusive." (PMID 20846416, 2010). "Exposure of tumour cells to oxaliplatin results in the release of high mobility group box 1 (HMGB1) protein, that activates DCs in a toll-like receptor-4 (TLR4)-dependent manner." (PMID 20924373, 2010). "The density of tumor-infiltrating lymphocytes (TILs) within the tumor tissue and the expression of HMGB1 in the cancer cells were examined via immunohistochemical analysis." (PMID 20846416, 2010). "There were significant differences among the three groups (ANOVA, p < 0.05), and a significant positive correlation between HMGB1 level and tumor size (Spearman correlation coefficients, γs = 0.457, p < 0.05)." (PMID 19476625, 2009). "Covalent DNA adducts generated by the platinating anti-tumor drugs cisplatin and oxaliplatin sequester nuclear HMGB1." (PMID 18179697, 2008).